BRCA1 (BRCA1 DNA repair associated)
Diseases named in the same sentence as BRCA1 in open-access papers (continued):
Sharing a sentence is not in itself a finding about the gene and the disease.
breast cancer (continued). "Second, is the BRCA1-mutation DNAme signature in WBCs functionally relevant or just simply an indicator of breast cancer risk?" (PMID 25067956, 2014). "None of these studies evaluated the prognostic significance of BRCA1 mutations in the context of breast cancer subtypes, histological types, tumor grade or received chemotherapy regimens." (PMID 24348864, 2014). "From this cohort, three at risk individuals and two familial breast cancer patients were positive for clearly pathogenic BRCA1 mutations and only six familial breast cancer patients were positive for clearly pathogenic BRCA2 mutations." (PMID 24906410, 2014). "The two major high-penetrance breast cancer susceptibility genes, BRCA1 and BRCA2, account for approximately 26% of all cases of hereditary breast and/or ovarian cancer (HBOC)." (PMID 24686251, 2014). "Inherited BRCA1 inactivating mutations are major determinants of breast and ovarian cancer risk, accounting for 46–68% of cases with a family history of breast cancer cases." (PMID 24845084, 2014). "A particular set of tumour suppressors associated with breast cancer is the Breast Cancer 1 and 2 gene set (BRCA1 and BRCA2)." (PMID 25548681, 2014). "This is the first comprehensive report, to our knowledge, of the associations of genetic variants with risk of developing breast cancer by tumor subtypes in BRCA1 and BRCA2 carriers." (PMID 25919761, 2014). "After the deletion of H3K9ac and/or E2F1 enrichment in BRCA1-mutated breast cancer, the transcription of DNMT1 was significantly down-regulated." (PMID 24502362, 2014). "Overall, BRCA1/2 mutations have a prevalence of ~5% in the general population and ~25% in the families with a history of breast cancer." (PMID 24944648, 2014). "While it is widely accepted that BRCA1+ leads to breast cancer by causing genome instability, the detailed mechanism for how BRCA1+ causes genome instability remain to be determined." (PMID 24884718, 2014). "Recent reports show that 53BP1 loss rescues BRCA1 deficiency and is associated with triple-negative and Brca1-mutated breast cancer." (PMID 24831086, 2014). "Chromatin immunoprecipitation analysis indicated that the levels of H3K9ac were reduced, and levels of H3K9me were increased around the methylated -132 site in BRCA1-mutated breast cancer." (PMID 24675476, 2014). "A study analyzing whole blood from BRCA1 mutation carriers identified a methylation signature that predicted sporadic breast cancer risk and death years in advance of diagnosis." (PMID 25473433, 2014). "From previous studies it is known that TNBCs resemble BRCA1-mutated breast cancers closely with regard to their genomic instability." (PMID 25083859, 2014). "A number of phase I and II studies have reported the successful applications of PARP inhibitors in BRCA1/2 mutation carries of ovarian and breast cancer, and phase III studies are underway." (PMID 24788697, 2014). "For example, a poorer overall survival of breast cancer BRCA1 4153delA mutation carriers compared with 5382insC, has been reported." (PMID 24348864, 2014). "We identified a missense variant (c.739G>T, p.Ala247Ser) of XRCC4 that correlated with an increased risk of non-BRCA1/2 breast cancer." (PMID 25360583, 2014). "Significantly, some of breast cancers with BRCA1 mutations have high frequencies of PTEN mutations, and the resulting PI3K/AKT activation induces the growth of those cancers." (PMID 25426449, 2014). "The second group consisted of 283 female BRCA1/2 mutation carriers and controls (mean age 48 years), half of whom had been diagnosed with breast cancer prior to enrolment." (PMID 24489760, 2014).
breast cancer (continued). "Loss of BRCA1 function leads to hydrogen peroxide generation in both epithelial breast cancer cells and neighboring stromal fibroblasts and promotes the onset of a reactive glycolytic stroma." (PMID 25136623, 2014). "Prior estimates have suggested more parts of women diagnosed with breast cancer before age 50 years carry germ-line mutations in BRCA1 than women after age 50 years." (PMID 25212775, 2014). "Although this article has focused on the utility of histopathologic features of breast cancers in the context of the classification of variants in the BRCA1 and BRCA2 genes, these results should also be useful in a range of other applications." (PMID 25857409, 2014). "HBOC syndrome accounts for 5–7% of all cases of breast cancer, and patients carrying the mutation have a lifetime risk for developing breast cancer of 50–80% and 30–50% for ovarian cancer (both BRCA1 and BRCA2)." (PMID 24959366, 2014). "Recent evidence indeed shows that BRCA1/2-mutated breast cancers are particularly sensitive to such agents." (PMID 24887359, 2014). "Mammographic density is similar among women at risk of either sporadic or BRCA1/2-related breast cancer." (PMID 25159706, 2014). "The complexes in breast tumours reflected aberration in Homologous recombination (HR), a key DSB-repair pathway which includes the breast cancer susceptibility genes BRCA1 and BRCA2." (PMID 25521701, 2014). "I.duc siRNA therapy would benefit women with atypical ductal hyperplasia or DCIS and women at high risk of developing breast cancer because of a family history of mutated BRCA1/2 or other familial breast cancer genes." (PMID 25927933, 2014). "Carriers of germline mutations in the BRCA1 gene have a significant increased lifetime risk for being diagnosed with breast cancer." (PMID 25460500, 2014). "The immunohistochemical and molecular profiles of TNBCs are similar to that of hereditary breast cancers that have mutations in the BRCA1 gene." (PMID 24479446, 2014). "The potential to predict breast cancer and offer preventive measures is an effective intervention in women with an inherited predisposition to breast cancer due to mutations in BRCA1/2 genes." (PMID 25067956, 2014). "Genetic screening for mutations in the breast cancer susceptibility genes BRCA1 and BRCA2 for families at high risk is a well established diagnostic modality." (PMID 24695549, 2014). "The Breast Cancer 1, early onset gene (BRCA1) located on chromosome 17q21.31 encodes a tumor suppressor that plays a critical role in the DNA damage response and repair pathways." (PMID 24915755, 2014). "Chromatin immunoprecipitation analysis indicated that the levels of H3K9ac and E2F1 around the E2F1 motif were only significantly decreased in BRCA1-mutated breast cancer." (PMID 24502362, 2014). "It has been also reported in the context of a positive family history of breast cancer and among BRCA1 and BRCA2 mutation carriers." (PMID 25277819, 2014). "We have also tested two Brca1-deficient mouse cell lines, 780 and 69, and two Brca1 wild-type cell lines, NK and Ras, which were derived from mammary tumors of MMTV-Neu and MMTV-Ras, respectively." (PMID 24962108, 2014). "The estimated cumulative risk of developing breast cancer by the age of 70 in BRCA1 and BRCA2 mutation carriers varies between 43% to 88%; similarly, between 11% to 59% of mutation carriers will develop ovarian cancer by the age of 70." (PMID 24698998, 2014). "In the present study, we assessed the disease subtype-specific associations of all 74 previously reported breast cancer susceptibility variants in 15,252 BRCA1 and 8,211 BRCA2 carriers." (PMID 25919761, 2014). "A recent paper demonstrated reduced TL in breast cancer patients who carried mutations in the BRCA1/2 genes compared with sporadic breast cancer cases." (PMID 24489760, 2014). "The breast cancer susceptibility gene (BRCA1) is commonly found to be mutated in hereditary breast and ovarian cancers." (PMID 24831086, 2014).
breast cancer (continued). "Given the importance of replication stress in epithelial cancer development and of an HR defect in breast cancer pathogenesis, both defects are candidate contributors to tumorigenesis in BRCA1-deficient mammary tissue." (PMID 25400221, 2014). "Up to half of all hereditary breast cancer cases can be attributed to autosomal dominant mutations in two genes, BRCA1 and BRCA2." (PMID 25159706, 2014). "Since then, germline mutations of BRCA1 have been found to be responsible for the hereditary type of breast cancer, which accounts for about 5-10% of all breast cancers." (PMID 25403427, 2014). "For example, PLD3 is identified as one of irradiation-responsive genes in human lymphoblastoid cells, serving as a genetic modifier for breast cancer susceptibility genes BRCA1 and BRCA2, suggesting a role of PLD3 in DNA damage response." (PMID 25478031, 2014). "Breast cancers arising in BRCA1 c.190T>C mutation carriers showed the peculiar histopathological features of the BRCA1-related breast tumor, with a propensity to be high grade invasive ductal or medullary carcinomas." (PMID 24516540, 2014). "Currently, oral intake of PARP inhibitors has shown a favorable therapeutic score for breast cancer with acceptably low toxicity in women with the BRCA1 and BRCA2 mutation." (PMID 24317580, 2014). "While BRCA1+ induces breast cancer by causing genome instability, most of the knowledge is known about somatic genome instability in breast cancer cells but not germline genome instability." (PMID 24884718, 2014). "The LST measure of HRD-related genomic scarring and its associated cutoff were found to significantly indicate BRCA1/2 deficiency in an independent validation data set of basal-like breast cancers as well as basal-like breast cancer cell lines." (PMID 25093514, 2014). "Breast cancers developing in patients with BRCA1 mutations, in addition to frequently being triple negative, also often express basal markers." (PMID 24579064, 2014). "BRCA1 promoter hypermethylation was observed in 16.4% of the breast cancer patients examined and was associated with BRCA1-, ER-, c-Myc overexpression, and the triple-negative phenotype." (PMID 25051360, 2014). "The frequency of unselected TNBC is similar to the frequency of BRCA1/2 mutations in individuals that were selected for inclusion because of a family history or bilateral breast cancer." (PMID 24961674, 2014). "BRCA1 mutations occur in approximately 50% of hereditary breast cancers, but a low expression of this gene was observed in 40% to 80% of cases." (PMID 24460909, 2014). "This is also true for BRCA1 carriers, in whom breastfeeding for 1 or 2 years was shown to be associated with a 32% and 49% reduction in breast cancer risk, respectively." (PMID 25436920, 2014). "The breast cancer susceptibility proteins, BRCA1 and BRCA2, have a key role in efficient HR response to DSBs." (PMID 24795863, 2014). "Yearly imaging with MRI has been shown to be a more sensitive means of screening for breast cancer than annual mammography for women at a high risk of cancer due to a BRCA1 or BRCA2 mutation, or at moderate risk of cancer due to a strong family history." (PMID 24667084, 2014). "As shown in Fig. 1Aii and B, BRCA1-mutated breast cancer exhibited hypermethylation of the first promoter (P < 0.001), especially around the -132 site (P < 0.001)." (PMID 24675476, 2014). "Women who carry mutations in the BRCA1 or BRCA2 (BRCA1/2) gene have a lifetime risk of 40% to 75% of developing breast cancer and up to a 40% risk of developing ovarian cancer." (PMID 24690515, 2014). "For example, epigenetic silencing by methylation of PTEN and BRCA1 genes is a hallmark of breast cancer." (PMID 25248717, 2014).
breast cancer (continued). "In Belarus and other Slavic countries, founder mutations in the BRCA1 gene are responsible for a significant proportion of breast cancer cases, but the data on contribution of these mutations to ovarian cancers are limited." (PMID 24770866, 2014). "This provided a biological mechanism by which rs3734091 conferred an increased susceptibility to non-BRCA1/2 breast cancer exclusively under a recessive model." (PMID 25360583, 2014). "Each of the HRD scores was significantly associated with BRCA1/2 deficiency in this breast cancer subtype." (PMID 25475740, 2014). "Women with harmful mutations in either BRCA1 or BRCA2 have a risk of breast cancer that is about five times the normal risk, and a risk of ovarian cancer which is about ten to thirty times the normal risk." (PMID 24523856, 2014). "Inherited BRCA1 germline mutation (BRCA1+) is a determined genetic predisposition leading to high risk of breast cancer." (PMID 24884718, 2014). "As shown in Figure1Aiii and1B, BRCA1-mutated breast cancer exhibited global promoter hypermethylation (P = 0.044), especially around the E2F1 motif (P = 0.017)." (PMID 24502362, 2014). "BRCA1 is a major tumor suppressor in breast cancer and it was implicated in numerous pathways resulting in anticarcinogenic functions." (PMID 25010005, 2014). "BRCA1, a well-known breast cancer tumor suppressor, is to associate with breast cancer risk and genetic susceptibility." (PMID 25426449, 2014). "To date, most individuals with a strong family history of breast cancer are only tested for BRCA1 and BRCA2 variants due to well established preventative treatment and surveillance guidelines." (PMID 24830819, 2014). "Mutation analysis of the BRCA1 gene revealed very low frequency of mutations in the BRCA1 gene in breast cancer patients with a family history of breast cancer." (PMID 24678344, 2014). "Breast cancer susceptibility gene 1 (BRCA1) is a major breast cancer suppressor gene and the most frequently mutated gene in hereditary breast cancer." (PMID 25010005, 2014). "In BRCA1- or BRCA2-mutated breast cancer, significant but transient and inconstant objective responses have been observed to olaparib in some studies, while other results were less conclusive." (PMID 25144364, 2014). "Similar associations were observed with PR-positive and PR-negative breast cancer for BRCA1 carriers." (PMID 25919761, 2014). "Approximately 20-25% of familial breast cancers can be attributed to a germline mutation in BRCA1 or BRCA2." (PMID 24667084, 2014). "In this study, the frequency of BRCA1/2 mutations ranged from ~8 to ~16% across four subtypes of breast cancer as defined by immunohistochemistry subtyping." (PMID 25475740, 2014). "Sporadic TNBC and BRCA1 germline mutation-associated breast cancers share many histopathologic and molecular features; however, only 10-20% of TNBCs harbor germline BRCA1 mutation." (PMID 25177489, 2014). "For example, breast cancer cells with mutations in the BRCA1 and BRCA2 are sensitive to inhibition of poly [ADP-ribose] polymerase (PARP1), whereas inhibition of PARP1 has little influence on survival and proliferation of normal cells with WT BRCA." (PMID 24150935, 2014). "Recently, EGFR, mTOR, and Poly (ADP-ribose) polymerase (PARP) inhibitors were among the therapeutic agents being studied in patients with TNBC and BRCA1-associated breast cancers." (PMID 24507701, 2014). "When the mutation status was evaluated according to the age of breast cancer onset, 11/285 (3.9%) patients with an age at diagnosis of ≤50 years were found to carry a BRCA1/2 mutation." (PMID 24944648, 2014). "In our previous studies, we screened a series of breast cancer susceptibility genes within the HR repair pathway, including BRCA1/2, PALB2, RAD50, and NBS1, in Chinese women." (PMID 25360583, 2014).
breast cancer (continued). "Here, we show that the first promoter-specific transcript 1 is the major PEMT mRNA species, and methylation of the -132 site is a key regulatory element for the PEMT gene in BRCA1-mutated breast cancer." (PMID 24675476, 2014). "The discovery of a meaningful clinical association of the BRCA1-3’UTR-variant in breast cancer further highlights the importance of studying such variants in appropriate cohorts to better understand their clinical potential." (PMID 24915755, 2014). "To date, several breast markers have been postulated, such as ER (ERα and ERβ), PR, Her-2, BRCA1 (breast cancer susceptibility gene) and β1 integrin." (PMID 24457087, 2014). "The study demonstrated that positive BRCA1 mutation status reduces the risk of distant recurrence and breast cancer-specific mortality with statistical significance." (PMID 24348864, 2014). "Recently, it has been shown that HRD, NtAi, and LST are highly correlated with each other and with BRCA1/2 deficiency (BRCA1 promoter methylation, germline, or somatic) in a breast cancer cohort that encompassed all the molecularly defined subtypes." (PMID 25093514, 2014). "Multivariate survival analysis indicated that lymph node metastasis was an independent prognostic factor for BRCA1-mutated breast cancer patients." (PMID 24502362, 2014). "The first clinical evidence for the importance of FANCJ was the identification of germ line sequence changes in FANCJ that were associated with early breast cancer in two individuals that displayed normal genotypes for BRCA1 and BRCA2." (PMID 25374583, 2014). "In general, BRCA1 (breast-cancer-associated gene 1) interacting with Oct-1 tends to cause breast cancer cells that show higher levels of chromosomal abnormalities." (PMID 24564526, 2014). "For example although ER-negative status clearly predicts BRCA1 mutation status, even ER-positive BRCA1-related breast cancers are more likely to be grade 3, CK14+, and show high mitotic rate compared with ER-positive sporadic cancers." (PMID 25857409, 2014). "Overall, TNBC accounts for about 15% of all breast cancers, but occurs more frequently in younger women and is the predominant subtype in individuals with a germline BRCA1 mutation." (PMID 24961674, 2014). "We have previously employed array comparative genomic hybridization (aCGH) to assess the genomic profiles of BRCA1-mutated breast cancers." (PMID 24887359, 2014). "In this study, we aimed to comprehensively evaluate the associations between XRCC4 genetic variants and non-BRCA1/2 breast cancer risk in a two-stage case-control study." (PMID 25360583, 2014). "Loss of BRCA1 coupled with MYC overexpression leads to the development of breast cancer and recent evidence has shown that MYC is druggable." (PMID 24550933, 2014). "We compared the log HR estimates for the breast cancer association of known breast cancer susceptibility variants for BRCA1 carriers, BRCA2 carriers, and for the general population using published data from the Breast Cancer Association Consortium (BCAC)." (PMID 25919761, 2014). "An example of a gene fully deleted in Hawaiian is F42A6.5, which has homology to human BRCA1, associated with breast cancer." (PMID 24694239, 2014). "BRCA1/2 mutations were detected in all three of the other breast cancer subtypes with frequencies ranging from 7.8 to 11.1%." (PMID 25475740, 2014). "Of note, BRCA1-associated breast cancers have been reported to have lower levels of SIRT1 relative to BRCA1 wild-type." (PMID 24971229, 2014).